APOC2 (apolipoprotein C2)
Diseases named in the same sentence as APOC2 in open-access papers (continued):
Sharing a sentence is not in itself a finding about the gene and the disease.
gastric cancer (7 papers, 2020 to 2025). A primary or metastatic malignant neoplasm involving the stomach. "In terms of transporters, In peritoneal metastases of gastric cancer, apolipoprotein C2 (APOC2) is markedly upregulated and promotes EMT in cancer cells via the CD36-mediated PI3K/Akt/mTOR signaling pathway, thereby enhancing their migratory capacity." (PMID 41278473, 2025). "Concerning PI3K/Akt/mTOR signaling, which regulates the EMT of gastric cancer cells, its aberrant phosphorylation was found to be caused by cooperation between CD36 and apolipoprotein C2 (APOC2)." (PMID 35873564, 2022). "Tandem Mass Tags identified differentially expressed proteins (DEPs) between peritoneal metastasis (PM) and gastric cancer tissues, and showed that APOC2 was highly expressed in PM tissues." (PMID 34459127, 2021). "Other identified antigens have been correlated to other types of cancer, namely ABCA13 in ovarian cancer, XIRP2 in gastric cancer, and APOC2 expression in Non-Small Cell Lung Cancer." (PMID 32245227, 2020). "APOC2 cooperates with CD36 to regulate EMT process via PI3K/AKT/mTOR signaling, which eventually promotes tumor progression and peritoneal metastasis in gastric cancer." (PMID 34459127, 2021). "Additionally, a negative correlation between HDAC3 and APOC2 protein levels was observed in NSCLC and gastric cancer (GC)." (PMID 38981044, 2024).
Sepsis (7 papers, 2011 to 2024). Sepsis is defined as life-threatening organ dysfunction caused by a dysregulated host response to infection. "Amyloid A is considered an acute inflammatory marker, whereas apolipoprotein C2 is an essential activator of lipoprotein lipase, which shows lower levels in preterm infants with sepsis." (PMID 38398801, 2024). "Similar to the reduced level of ApoA1 and A2 reported in sepsis, plasma levels of ApoC2, C3, and ApoD decreased with increasing NEC severity." (PMID 33133078, 2020). "A prospective cohort study differentiates NEC from sepsis using apoSAA score, which is calculated from plasma apolipoprotein C2 (apoC2) and SAA; the results show that the apoSAA score is helpful in the early diagnosis of NEC and the differentiation of NEC from sepsis." (PMID 36186788, 2022). "The ApoSAA score calculated from plasma apoC2 and SAA concentrations could effectively discriminate sepsis/NEC cases from controls, with a specificity ranging from 55 to 95% and a sensitivity from 90 to 100%, depending on the cutoff value." (PMID 33425815, 2020).
Hypertension (6 papers, 2006 to 2026). The presence of chronic increased pressure in the systemic arterial system. "Furthermore, higher levels of APOC2 were associated with decreased hazard for hypertension (HR = 0.80, p = 0.047)." (PMID 41316897, 2026).
acute pancreatitis (5 papers, 2012 to 2023). An acute inflammatory process that leads to necrosis of the pancreatic parenchyma. "For Type I patients presenting with acute pancreatitis from APOC2 gene mutations, infusion of fresh frozen plasma from normal donors can be considered for rapidly lowering TG." (PMID 34838008, 2021). "In humans, APOC2 loss-of-function mutations can promote a prodigious rise in plasma TG levels due to chylomicronemia and consequently can provoke acute pancreatitis." (PMID 32849290, 2020). "Chinese patients with HTG-associated acute pancreatitis (HTG-AP) were screened for rare nonsense, frameshift, missense or canonical GT-AG splice site variants in LPL and four other lipid metabolism-related genes (APOC2, APOA5, GPIHBP1 and LMF1) by Sanger sequencing." (PMID 37550668, 2023). "Bi-allelic pathogenic mutations in LPL, APOC2, GPIHBP1, APOA5, or LMF1, that lead to reduced LPL action, are used to confirm familial chylomicronemia syndrome, a rare autosomal recessive disorder characterized by severe elevation of TG levels, eruptive cutaneous xanthomas and acute pancreatitis." (PMID 32849290, 2020).
Alzheimer disease (5 papers, 2015 to 2024). A progressive, neurodegenerative disease characterized by loss of function and death of nerve cells in several areas of the brain leading to loss of cognitive function such as memory and language. "Interestingly, APOC2 has been found to be associated with Alzheimer’s disease." (PMID 32823525, 2020).
amyloidosis (5 papers, 2016 to 2024). A disorder characterized by the localized or diffuse accumulation of amyloid protein in various anatomic sites. "AA amyloidosis was found in 4.2% (n = 5) of patients and ApoC2 amyloidosis was documented in 0.8% (n = 1) of surveyed patients." (PMID 38768126, 2024). "Transthyretin (ATTR) amyloidosis occurring as hereditary (ATTRv) or age-related (ATTRwt) forms and light chain (AL) amyloidosis are the most frequent subtypes, whereas AA amyloidosis, localized amyloidosis, and rare forms such as ApoC2 amyloidosis are less common." (PMID 38768126, 2024). "Based on the fact that affected patients with amyloidosis also displayed hypotriglyceridemia and increased plasma levels of HDL-C as compared with non-carriers in the family, we next screened several candidate genes including the APOC3, APOC1, APOC2, APOC4, APOA4, APOA5 and APOE genes." (PMID 26790392, 2016).
cervical cancer (5 papers, 2021 to 2024). A primary or metastatic malignant neoplasm involving the cervix. "Although APOC2 has been implied as a biomarker in pancreatic and cervical cancer, an overexpression of APOC3 has been described in ovarian cancer and in the recurrent disease of small-cell lung cancer patients." (PMID 39194522, 2024). "Conversely, in cases of cervical cancer leading to mortality, APOC2 levels were significantly lower than in asymptomatic cases." (PMID 38067270, 2023). "In addition, according to the serum APOC2 expression level, the radiation treatment outcome of patients with locally advanced cervical cancer can be predicted and evaluated." (PMID 34459127, 2021). "Regarding post-treatment prognosis in cervical cancer, APOC2 might be a prospective marker, given the absence of a substantial difference between the control group and asymptomatic patients." (PMID 38067270, 2023).
Familial Chylomicronemia (5 papers, 2017 to 2025). "Moreover, a homozygous point mutation in the ApoC2 gene, resulting in no measurable plasma ApoC2 in infancy, causes severe hyperchylomicronemia and encephalopathy." (PMID 39798876, 2025).
acute myeloid leukemia (4 papers, 2021 to 2024). Acute myeloid leukemia (AML) is a group of neoplasms arising from precursor cells committed to the myeloid cell-line differentiation. "It has been previously reported that APOC2 interacts with CD36 to trigger downstream signaling in acute myeloid leukemia (AML) and atherosclerosis." (PMID 34459127, 2021). "In acute myeloid leukemia (AML), we found that APOC2 acts with CD36 to promote leukemia growth by activating the LYN-ERK signaling." (PMID 37226083, 2023).
Cognitive impairment (4 papers, 2015 to 2025). Abnormal cognition is characterized by deficits in thinking, reasoning, or remembering. "High serum levels of APOC2 are associated with cognitive impairment, and the exact underlying mechanism of action is unclear." (PMID 37008043, 2022).
coronary artery disease (4 papers, 2015 to 2024). "First, we could not compare plasma levels of ApoC-2, ApoA-1, 14–3–3 protein ζ/δ, and ITIH4 in patients with TAK with those in patients with other inflammatory diseases, such as systemic lupus erythematosus, rheumatoid arthritis, coronary artery diseases, and other bacterial infectious diseases." (PMID 34556808, 2021).
COVID-19 (4 papers, 2021 to 2023). A disease caused by infection with severe acute respiratory syndrome coronavirus 2. "Pathways depicting cholesterol, HDL and LDL metabolism (WP430, WP5109, WP4522, WP3601) are also among the top 10 pathways that have reduced activity in COVID-19 patients with significant reductions in APOA1, APOA2, APOC2, APOC3, APOB protein abundance." (PMID 36189295, 2022).
leukemia (4 papers, 2021 to 2025). A malignant (clonal) hematologic disorder, involving hematopoietic stem cells and characterized by the presence of primitive or atypical myeloid or lymphoid cells in the bone marrow and the blood. "APOC2 also promotes the growth of leukemia through the CD36‐ERK signaling." (PMID 34459127, 2021). "In vivo APOC2 and CD36 knockdown reduces leukemia burden and engraftment to bone marrow, spleen, and peripheral blood; therefore APOC2-CD36 signaling may be an attractive therapeutic target." (PMID 36568966, 2022).
non-small cell lung carcinoma (4 papers, 2020 to 2025). A group of at least three distinct histological types of lung cancer, including non-small cell squamous cell carcinoma, adenocarcinoma, and large cell carcinoma. "In a non-small cell lung cancer study, Kla of apolipoprotein C-2 (APOC2) at K70 promotes Treg enhancement and immunotherapy resistance by inducing elevated free fatty acid levels." (PMID 41181157, 2025). "In non-small cell lung cancer, APOC2 K70 lactylation is substantially upregulated in patients resistant to immunotherapy and is negatively linked to overall survival in both non-small cell lung cancer and gastric cancer." (PMID 40994548, 2025). "Lactylome analysis of non-small cell lung cancer revealed that APOC2 is the only upregulated lactylated protein involved in lipid transport and metabolism." (PMID 40994548, 2025). "A specific antibody against the APOC2 K70 lactylation site has been developed, showing a positive correlation with immunotherapy resistance in non-small cell lung cancer." (PMID 41181157, 2025). "In non-small cell lung cancer (NSCLC), anti-APOC2 K70 lactylation antibodies neutralize extracellular APOC2, suppressing tumor growth and potentially offering combinational approaches for patients with NSCLC and other APOC2-associated diseases." (PMID 40849305, 2025).
liver disease (3 papers, 2016 to 2024). "Consistent with other studies, we demonstrated an increase in apoC2/C3 levels post-treatment in non-cirrhotic patients irrespective of ribavirin exposure and provide further evidence that more advanced liver disease is associated with low levels of these apolipoproteins pre- and post-treatment." (PMID 30884773, 2019). "Lipoprotein lipase activity has been shown to inversely correlate with HCV RNA levels, and low apoC2 levels correlate with increased HCV infection and more advanced liver disease." (PMID 30884773, 2019).
pancreatic cancer (3 papers, 2021 to 2023). "In the field of tumor‐related research, it has been shown that APOC2 is significantly associated with survival of pancreatic cancer." (PMID 34459127, 2021). "Pancreatic cancer cells with high APOC2 expression show enhanced cell invasion capability." (PMID 34459127, 2021).
Stroke (3 papers, 2017 to 2024). Sudden impairment of blood flow to a part of the brain due to occlusion or rupture of an artery to the brain. "APOC4 correlates with stroke recovery, while APOC2 is involved in the pathophysiology of post-stroke depression." (PMID 35754821, 2022). "A1AG1, CRP, and LBP were upregulated, while TTR, ApoC2, and RBP4 were downregulated in patients with stroke and AF, compared to patients with stroke without AF." (PMID 38886511, 2024). "In contrast, the levels of transthyretin (TTR), apolipoprotein C-II (ApoC2), and retinol-binding protein 4 (RBP4) were lower in patients with stroke and AF compared to those without AF." (PMID 38886511, 2024).
esophageal cancer (2 papers, 2021 to 2025). A primary or metastatic malignant neoplasm involving the esophagus. "The comparison between esophageal tumors and healthy tissue showed BIRC5 (p = 2.61E−08), APOC2 (p = 3.23E−08), CENPF (p = 4.38E−08), STMN1 (p = 5.74E−08), and HNRPC (p = 8.21E−08) to be five leading genes overexpressed in esophageal cancer." (PMID 33828156, 2021). "We noted that compared to normal tissue, BIRC5, CENPF, STMN1, APOC2, and HNRPC were the five most significantly upregulated genes in esophageal cancer." (PMID 33828156, 2021).
gastrointestinal stromal tumor (2 papers, 2021 to 2024). "MiRNA 4510 has been reported to be involved in migration, invasion, and proliferation in gastrointestinal stromal tumors by targeting APOC2 expression." (PMID 38741808, 2024). "Inhibiting APOC2 expression can inhibit the invasion of gastrointestinal stromal tumor cells." (PMID 34459127, 2021).
gestational hypertension (2 papers, 2024 to 2026). "The profile differentiating gestational hypertension (GAH) from chronic hypertension (CAH) was linked to lipid metabolism (HRG, APOA4, APOC2)." (PMID 41683823, 2026).
Hernia (2 papers, 2018). "APOC2 is one of the biomarkers that have been used in differentiating bladder cancer from hernia." (PMID 30517191, 2018). "Apolipoproteins were analyzed with an immunoassay for multiplexed detection of APOA1, APOA2, APOB, APOC2, APOC3, and APOE, and all six proteins were found to be significantly elevated in urine samples of BC patients when compared to controls (hernia patient volunteers)." (PMID 30544619, 2018).
renal failure (2 papers, 2016 to 2024). "Our data suggest the AIM2 and Dectin-1 inflammasome pathways, along with complement cascade elements C2 and C8, and lipidic disorders associated with apolipoprotein C-II (APOC2), can be associated with the development of renal failure in Bothrops snakebites." (PMID 38536893, 2024).
anemia (1 paper, 2018). A reduction in the number of red blood cells, the amount of hemoglobin, and/or the volume of packed red blood cells. "This is in agreement with our findings of the anemia phenotype being resolved in adult Apoc2 mutant mice." (PMID 29615667, 2018). "The finding of anemia in young Apoc2 mutant mice suggests that our discovery of the role of LPL activity in zebrafish hematopoiesis is relevant to mammalian biology." (PMID 29615667, 2018). "However, the profound anemia phenotype was alleviated in adult Apoc2 mutant mice (3–4 months), though mutant mice still had significantly less white blood cells." (PMID 29615667, 2018).
autoimmune disease (1 paper, 2021). A disorder resulting from loss of function or tissue destruction of an organ or multiple organs, arising from humoral or cellular immune responses of the individual to their own tissue constituents. "While little is known about the role of ApoC-2 in autoimmune diseases, the role of its receptor CD36 is more established." (PMID 34556808, 2021).
chronic lymphocytic leukemia (1 paper, 2019). "Some of the genes detected in our study include the apolipoprotein gene cluster (APOC1, APOC2, APOE), which are shown to have tight linkage with a chronic lymphocytic leukemia-associated translocation breakpoint." (PMID 31013791, 2019).
clear cell renal cell carcinoma (1 paper, 2025). "This study aimed to investigate the role and underlying mechanism of apolipoprotein C2 (APOC2) in the progression of clear cell renal cell carcinoma (ccRCC)." (PMID 41296440, 2025). "To elucidate the regulatory role of APOC2 in the biological behavior of clear cell renal cell carcinoma (ccRCC) cells, we established APOC2 knockdown models in 786-O and OSRC-2 cell lines." (PMID 41296440, 2025). "Our study identifies APOC2 as a novel oncogenic regulator in clear cell renal cell carcinoma." (PMID 41296440, 2025).
coronary artery stenosis (1 paper, 2021). "The analysis showed that apolipoprotein C-II (APOC2), dedicator of cytokinesis protein 2 (DOCK2), ligand 7 (CXCL7) and vitamin D binding protein (VTDB) were activated, and complement 4A (C4A) were suppressed in diabetic patients and were associated with severe coronary artery stenosis." (PMID 34948066, 2021).
esophageal tumors (1 paper, 2021). "The stage-based assessment of overexpressed genes showed significant overexpression of BIRC5, APOC2, CENPF, STMN1, and HNRPC across all cancer stages including early, locally advanced and metastatic esophageal tumors." (PMID 33828156, 2021).
glioma (1 paper, 2020). A benign or malignant brain and spinal cord tumor that arises from glial cells (astrocytes, oligodendrocytes, ependymal cells). "For the VSIG4 peptide GSDPVTIFLR, a sensitivity of 71.4% and specificity of 90.0% can be estimated at a cut-off of 36.2 fmol/μg protein and TAAQNLYEK (APOC2) can discriminate PCNSL from glioma patients at a cut-off of 8.3 fmol/μg with a sensitivity and specificity of 84.6% and 77.7%, respectively." (PMID 32610669, 2020). "The tryptic peptide TAAQNLYEK from apolipoprotein C-II (APOC2) was found to be higher abundant in the CSF of the PCNSL patients in comparison with MS and glioma patients." (PMID 32610669, 2020).
Hepatitis (1 paper, 2017). Inflammation of the liver. "After 18 weeks, HFD mice developed NASH like features with severe steato-hepatitis and fibrosis, increased hepatic content of triacylglycerol and cholesterol and expression of SREPB1c, FAS, ApoC2, PPARα and γ, α-SMA, α1 collagen and MCP1 mRNAs." (PMID 28202906, 2017).
hepatocellular carcinoma (1 paper, 2025). A malignant tumor that arises from hepatocytes. "APOC2 protein expression was confirmed in normal colon, CRC, and hepatocellular carcinoma tissues using The Human Protein Atlas database." (PMID 41303528, 2025).
lung carcinoma (1 paper, 2024). "To assess the immunological effects of APOC2 K70 mutations on tumor immune microenvironment of lung cancer, we established APOC2Sh rescue ‐WT and ‐K70R murine lung cancer cell lines (LLC cells)." (PMID 38981044, 2024).
ovarian tumors (1 paper, 2018). "Protein APOC2 was differently expressed in BOT, which suggests its role as a BOT marker and it could be useful in differential diagnosis of ovarian tumors." (PMID 30065196, 2018). "The significance of APOC2, APOC4, ORM1, SERPINA1, and SERPINA10 in differential diagnosis of ovarian tumors was not confirmed." (PMID 30065196, 2018).
renal carcinoma (1 paper, 2025). A carcinoma arising from the epithelium of the renal parenchyma or the renal pelvis. "Moreover, APOC2 may serve as a prognostic biomarker and a metabolic vulnerability in renal cancer." (PMID 41296440, 2025).
spinocerebellar ataxia type 12 (1 paper, 2018). Spinocerebellar ataxia type 12 (SCA12) is a very rare subtype of type I autosomal dominant cerebellar ataxia (ADCA type I). "Apolipoprotein C2 deficiency is related to a lipid encephalopathy and spinocerebellar ataxia type 12." (PMID 30114292, 2018).
transmissible spongiform encephalopathies (1 paper, 2011). "Several studies have also reported the involvement of many members of the apolipoprotein gene family (ApoA1, ApoA4, ApoC1, ApoC2, ApoC3 and ApoD) in transmissible spongiform encephalopathies." (PMID 21629698, 2011).